PHYKPL (5-phosphohydroxy-L-lysine phospho-lyase)
Description:
Catalyzes the pyridoxal-phosphate-dependent breakdown of 5-phosphohydroxy-L-lysine, converting it to ammonia, inorganic phosphate and 2-aminoadipate semialdehyde.
Synonyms: AGXT2L2; MGC15875; PHLU
Tractability: PROTAC: ubiquitination databases record sites on it; its protein half-life has been measured.
Target class: Enzyme; Lyase
Gene: Protein-coding gene on chromosome 5 (178,207,144 to 178,233,208, reverse strand). Ensembl gene ENSG00000175309.
Subcellular location: Mitochondrion
Subcellular location (Human Protein Atlas): Mitochondria
Pathways (Reactome):
Extracellular matrix organization: Collagen degradation
Metabolism: Lysine catabolism
Gene Ontology:
Molecular function: identical protein binding; protein binding; pyridoxal phosphate binding
Cellular component: mitochondrial matrix; mitochondrion
Genetic constraint (gnomAD): Loss-of-function variants: 42 observed, 53.28 expected, observed/expected ratio (o/e) 0.79, 90% interval 0.62 to 1.02. The upper end of that interval is the gene's LOEUF score, 1.02, which puts it in group 4 of 6, group 1 being the genes least tolerant of losing a copy. Missense variants: 655 observed, 608.74 expected, observed/expected ratio (o/e) 1.08, 90% interval 1.01 to 1.15. Synonymous variants: 264 observed, 243.72 expected, observed/expected ratio (o/e) 1.08, 90% interval 0.98 to 1.2.
Gene-disease validity (ClinGen):
ClinGen rates the evidence that PHYKPL causes each of these diseases.
phosphohydroxylysinuria (autosomal recessive): Limited.
Homologues: Orthologues: chimpanzee PHYKPL (99% identical), macaque PHYKPL (97% identical), rat Phykpl (88% identical), guinea pig PHYKPL (87% identical), mouse Phykpl (87% identical), dog PHYKPL (85% identical), pig PHYKPL (80% identical), rabbit PHYKPL (78% identical), zebrafish phykpl (66% identical). Paralogues in human: ETNPPL (65% identical), AGXT2 (32% identical), OAT (24% identical), ABAT (21% identical).
Diseases named in the same sentence as PHYKPL in open-access papers:
PHYKPL is named in the same sentence as 2 diseases in open-access papers, as found by Europe PMC text mining. Sharing a sentence is not in itself a finding about the gene and the disease.
PHYKPL shares sentences with these, for which no sentence is quoted: cardiovascular disease (1 paper); Stroke (1).